ZEB1 (zinc finger E-box binding homeobox 1)
Diseases named in the same sentence as ZEB1 in open-access papers (continued):
Sharing a sentence is not in itself a finding about the gene and the disease.
breast carcinoma (continued). "A team of scientists led by Lee73 showed that miR-205 inhibits both Zeb1 and Zeb2 mRNAs in the breast cancer cell lines MCF7, MDA231, and SK-BR-3." (PMID 33414456, 2021). "Taken together, in this study, we found that human endogenous and exogenous SLFN5 can maintain or restore breast cancer cells with epithelial morphology by transcriptional suppression of ZEB1 expression." (PMID 32488136, 2020). "Consistently, irradiation therapy in breast cancer cells results in massive miR-205 downregulation, accompanied by upregulation of ZEB1, which can be completely reversed by inhibition of ATM or direct depletion of ZEB1." (PMID 32266287, 2020). "These genes were upregulated by knockdown of ZEB1 in a metastatic breast cancer cell line and are thus likely to be targets of ZEB1-mediated transcriptional repression." (PMID 32005677, 2020). "Here, we summarize the recent discoveries of the functions and mechanisms of ZEB1 to understand the role of ZEB1 in EMT regulation in breast cancer." (PMID 32014049, 2020). "A growing body of evidence has suggested that Zeb1 is a determinant of poor survival in human breast cancer." (PMID 33046710, 2020). "In a large cohort of human breast cancer subjects, high levels of ZEB1 were shown to have positive relationships with Bcl-xl and cyclin D1, predicting a poor response to chemotherapy." (PMID 32014049, 2020). "RUNX1 suppresses breast cancer growth by repressing the activity of breast cancer stem cells and inhibiting ZEB1 expression directly." (PMID 32498288, 2020). "BCL6 induces EMT by promoting the ZEB1-mediated transcription repression of E-cad in breast cancer cells." (PMID 31988090, 2020). "Herein, we demonstrated that specific inhibition of CDK4/6 was able to block tumor metastasis of breast cancer by destabilizing the ZEB1 protein in vitro and in vivo." (PMID 32296027, 2020). "Instead, SLFN12 acted through inhibiting the translation of c-myc protein, similar to how SLFN12 modulates the expression of ZEB1 in breast cancer." (PMID 32987632, 2020). "Here the authors show that tumor endothelial Jagged1 induces activation of Notch1 signaling and increases Zeb1 expression in neighboring breast cancer stem cells, promoting tumor aggressiveness." (PMID 33046710, 2020). "TAK-733 (as 1 μM) showed significant effects on miR-221/ZEB1 reduction and breast cancer cell proliferation and migration capacity." (PMID 33327491, 2020). "In mammary gland and breast carcinoma, ZEB1 inhibits CDH1 expression by interacting with DNA methyltransferase 1 (DNMT1)." (PMID 32796736, 2020). "Previously investigated in breast cancer and our results suggested the possible involvement of Snail, Twist, and ZEB1 in the down-regulation of E-cadherin during the SMG." (PMID 32079291, 2020). "We thus examined the relationship between the mRNA expression levels of TGFB1 (TGFβ), CTNNB1 (β-catenin), SNAI1, SNAI2 and ZEB1 and those of Sipa1 in TCGA breast cancer patient samples." (PMID 32193333, 2020). "In our previous studies, ELK3 expression was significantly correlated with cell migration and invasion in breast cancer, and ZEB1 regulated the transcriptional activity of ELK3 to repress E-cadherin expression in breast cancer cells." (PMID 32414208, 2020). "GRHL2 suppresses EMT in a breast cancer cell line by directly repressing the ZEB1 promoter, while key EMT suppressors are directly transactivated by GRHL2, including MIR200B, MIR200A, MIR429 and Ovol2." (PMID 32005677, 2020). "In the present study, we provide evidence that the specific inhibition of CDK4/6 results in a significant decrease in ZEB1 protein stability that subsequently blocks tumor metastasis in breast cancer both in vitro and in vivo." (PMID 32296027, 2020). "In summary, we demonstrated an alternative mechanism for the CDK4/6-USP51 axis in regulating breast cancer metastasis that supplements the deubiquitination and stabilization of ZEB1." (PMID 32296027, 2020).
breast carcinoma (continued). "In general, the GRHL2/ZEB1 feedback loop was identified as a key regulator of EMP and associated traits in breast cancer, lung cancer, colorectal cancer and ovarian cancer." (PMID 32676163, 2020). "Remarkably, CD24 is a direct target of Wnt1 in breast cancer, while CD47 is an indirect target of Wnt signaling mediated by SNAI1 and ZEB1 in breast cancer." (PMID 33234169, 2020). "ZEB1 also plays a vital role in embryonic development and cancer progression, including breast cancer progression." (PMID 32014049, 2020). "The aberrant expression of ZEB1 is thought to be connected with tumorigenesis and poor prognosis in various tumors, especially in breast cancer." (PMID 32014049, 2020). "The new findings related to posttranslational modifications that regulate ZEB1 provide an alternative pathway for precision medicine to treat breast cancer by targeting ZEB1." (PMID 32014049, 2020). "To further strengthen the pathological correlation between Notch1-Zeb1 signaling and stemness properties in human breast cancer, we performed immunohistochemical staining for Zeb1, NICD and ALDH1 in 175 cases of primary breast carcinoma." (PMID 33046710, 2020). "It functions as an oncogene in breast cancer to facilitate the process of epithelial-to-mesenchymal transition, inducing the expression of zinc finger E-box-binding homeobox 1 (ZEB1) and promoting the conversion of CD24high cells to CD44high cancer cells." (PMID 33110456, 2020). "These secreted factors were upregulated in mesenchymal cells by ZEB1-repressed miRNA clusters, promoting autocrine signaling, which was followed by increased VM in breast cancer cells." (PMID 32014049, 2020). "This review will focus on the EMT transcription factor ZEB1 and its functions in the oncogenesis and development of breast cancer." (PMID 32014049, 2020). "To further examine the pathological correlations between p-USP51, ZEB1, and CDK4/6 activity, we performed immunohistochemical staining for p-RB, p-USP51, and ZEB1 in 265 cases of human primary breast carcinoma." (PMID 32296027, 2020). "Here, we show that Zeb1 depletion suppresses stemness, colonization and the phenotypic plasticity of breast cancer." (PMID 33046710, 2020). "We found that compared with normal breast tissue, the expression of SIX‐1, lncATB and ZEB1 was increased in breast cancer tissue, while the expression of miR‐200c‐3p was decreased." (PMID 32227618, 2020). "Critically, gene upregulation by the ZEB1-YAP complex correlated with gene expression signatures of claudin-low breast cancer, a breast cancer subtype overall exhibiting an EMT phenotype." (PMID 32292603, 2020). "Abnormal expression of ZEB1 has been reported in various human cancers, including pancreatic cancer, lung cancer, liver cancer, colon cancer, and breast cancer." (PMID 32014049, 2020). "Of note, phosphorylation of signal transducer and activator of transcription 3 (STAT3) can translocate into the nucleus to recruit on ZEB1 promoter, resulting in ZEB1 nuclear translocation in breast cancer cells." (PMID 33058500, 2020). "We previously reported that increased expression of Zeb1 in breast cancer cells induces VEGFA production, thus promoting tumor angiogenesis and propagation." (PMID 33046710, 2020). "The expression level of ZEB1 is increased in triple-negative breast cancers (TNBCs) and basal-like breast cancers compared to the luminal subtype." (PMID 32014049, 2020). "According to the previous reports, CDKL2 is a newly discovered regulator enhancing EMT and increasing CD44-high subpopulation through upregulating ZEB1 expression in breast cancer." (PMID 33178818, 2020). "GRHL2 has been identified as an MET inducer in breast cancer, where it forms a mutually inhibitory feedback loop with ZEB1, an EMT-TF." (PMID 32676163, 2020). "LPA activated the G-protein coupled receptor LPAR1, which promotes the upregulation of miR-21 in breast cancer cells through a PI3K/ZEB1-dependent pathway." (PMID 31952362, 2020).
breast carcinoma (continued). "Enhanced metastatic potential was associated with overexpression of ZEB1 in a mouse xenograft model of breast cancer, suggesting the role of ZEB1 in invasion and metastasis of human tumors." (PMID 32014049, 2020). "A similar positive feedback regulation between HA and other cancer promoting factors, such as ZEB1 and Akt, has been identified, for example in breast cancer." (PMID 31820036, 2020). "Another issue that would be worth addressing is a potential concerted action with the ZEB1 transcription factor, as described in the context of breast cancer as ZEB1 represents one of the CMS4-classifier genes." (PMID 33126419, 2020). "Depletion of Zeb1 in breast cancer disrupts this positive feedback loop in the tumor perivascular niche, eventually decreasing CSC phenotypes and tumor angiogenesis." (PMID 33046710, 2020). "While Snail, Slug, Twist1, and ZEB1 are direct targets of Wnt/β-Catenin signaling in breast cancer, ZEB2 is inclined to be an upstream factor of Wnt/β-Catenin signaling." (PMID 33234169, 2020). "In this study, we aimed to investigate the relationship between PDGF-B/PDGFR signaling and ZEB1 in breast cancer cell proliferation and metastatic phenotype, as well as explore the underlying mechanisms." (PMID 32850368, 2020). "EMT in breast cancer cells is directly regulated by several TFs, such as Zeb1, Snail and Twist 55, and these TFs also are involved in regulating cancer cell stemness 56-58; thus the expression of these TFs was examined." (PMID 32724475, 2020). "Meanwhile, miR-144 acts as a tumor suppressor in breast cancer by means of impeding ZEB1/2-induced EMT process." (PMID 32355466, 2020). "In breast cancer cells, it has been shown that yes-associated protein 1 (YAP) recruits ZEB1 and turns it into a transcriptional activator, upon which they drive a common ZEB1/YAP target gene set." (PMID 32796736, 2020). "In breast cancer, endothelial Jagged1 was found to activate Notch1 in neighboring breast cancer stem cells, upregulating Zeb1, which in turn increases Vegfa production and further activates the tumor neovasculature." (PMID 33198378, 2020). "Oppositely, in basal-like or basal CD44hi breast cancer cells, high expression levels of ZEB1 were controlled by H3K4me3 and H3K79me2 in its promoter, which did not have H3K27me3, indicating active transcription." (PMID 32014049, 2020). "Collectively, our data support the conclusion that ERα and ZEB1 regulate the expression of SOX9 via regulating miR-190 expression in breast cancer cells." (PMID 30658681, 2019). "The loss of E-cadherin and increased expression of mesenchymal markers (N-cadherin, Snail, Twist, Vimentin, and Zeb1) were used as EMT indicators in breast cancer cells." (PMID 31889895, 2019). "Together, these data suggest that ZEB1 functions as a key component of RAE1-mediated EMT in breast cancer." (PMID 30814639, 2019). "To explore in more detail the link between PKC and ZEB1, we investigated a panel of breast cancer cells of different subtypes (luminal and basal-like) and different degrees of aggressiveness." (PMID 31828042, 2019). "We identified three groups of M-genes that can be distinguished by their responsiveness to TGF-β and ZEB1 pathways, and demonstrated the distinct biological impacts of the three M clusters in breast cancer patient survival and cell motility regulation." (PMID 31275609, 2019). "The causality of this association was further confirmed using PKCα silencing approaches, which triggered a pronounced downregulation of ZEB1 in several breast cancer cell lines." (PMID 31828042, 2019). "We also previously reported that ZEB1/2 are preferentially recruited to the promoter region of ESRP1 where they suppress the transcription of ESRP1 in breast cancer cells." (PMID 31682640, 2019). "qRT‐PCR results revealed that Jagged1, ZEB1 and Bmi1 mRNAs were up‐regulated in breast cancer tissues compared with matched adjacent tissues." (PMID 31599500, 2019).
breast carcinoma (continued). "In vitro experiments showed that NNT-AS1contributes to breast cancer pathogenesis via alteringmiR-142-3p/ZEB1 axis." (PMID 31210440, 2019). "In breast cancer cells, honokiol inhibits the recruitment of Stat3 on mesenchymal transcription factor Zeb1 promoter, resulting in decreased Zeb1 expression and nuclear translocation." (PMID 31877856, 2019). "In this work we have approached the question of how the activity of the EMT transcription factor ZEB1 can be modulated in breast cancer cells." (PMID 31828042, 2019). "ZEB1, a crucial member of the zinc finger homeodomain transcription factor family, is overexpressed in breast cancer cells and promotes breast tumorigenesis and cancer progression." (PMID 30658681, 2019). "In this study, we aimed to explore the correlation between ZEB1 protein expression and neoadjuvant chemotherapy sensitivity in patients from our weekly paclitaxel- and cisplatin-based neoadjuvant trial in breast cancer." (PMID 30976202, 2019). "After removing ZEB2 from consideration, ZEB1 was most significantly correlated with stromal infiltration in breast cancer (r2 = 0.65, p = 3.99 × 10−180)." (PMID 31780722, 2019). "A key finding of this study is that ZEB1 is highly expressed in basal-like breast cancer cells, which are known to possess a high metastatic potential." (PMID 31828042, 2019). "Taken together, our findings unveil an unforeseen regulatory pathway comprising PKCα and ZEB1 that promotes the activation of the EMT in breast cancer cells." (PMID 31828042, 2019). "Given the relevance of ZEB1 in cancer progression, we were particularly interested in exploring if the migratory and invasive capacities of breast cancer cells were altered upon PKCα RNAi depletion, similar to when ZEB1 is down-regulated." (PMID 31828042, 2019). "Our result is supported by research by Lin, which showed that ZEB1 and ZEB2 mRNA expression as well as protein expression were associated with poor survival in breast cancer." (PMID 30976202, 2019). "We further demonstrated a mechanism for zinc-finger E-box binding homeobox 1 (ZEB1)-miR-190-SOX9 axis-mediated resistance to endocrine therapy in breast cancer." (PMID 30658681, 2019). "Adipocyte-CM treated breast cancer cells upregulated the levels of mesenchymal markers (Vimentin and Zeb1) and downregulated epithelial marker (E-cadherin) indicating that adipocyte CM can promote EMT." (PMID 31383893, 2019). "The dynamic EMT and MET was also observed in parental and HCC38 cells delineated by EpCAM profiling, in Zeb1 driving CD44Low to CD44High cellular plasticity and in mammary carcinoma mouse MyPT models delineated by E-cadherin profiling." (PMID 31234417, 2019). "In this work, we unveiled an unforeseen role of PKCα in the upregulation of ZEB1 levels in breast cancer cells." (PMID 31828042, 2019). "In this study, we have examined the expressing pattern of ZEB1 in different subtypes of human and mouse breast cancers." (PMID 31324807, 2019). "In this study, while interrogating human databases, we uncover a remarkable decrease in relapse-free survival of breast cancer patients expressing high ZEB1 levels in the stroma." (PMID 31324807, 2019). "Using a mouse model of breast cancer, we show that ZEB1 inactivation in stromal fibroblasts suppresses tumour initiation, progression and metastasis." (PMID 31324807, 2019). "In conclusion, our study demonstrated that RAE1 promotes progression of breast cancer cells by activating ZEB1 at the transcription level and revealed the positive correlation between RAE1 and ZEB1 in breast cancer metastasis." (PMID 30814639, 2019). "In this study, the authors show in a mouse model of breast cancer, that Zeb1 expression in stromal cells is required for tumour formation and metastasis." (PMID 31324807, 2019).
breast carcinoma (continued). "A strong correlation was observed between ZEB1 and PKCα levels in breast cancer cells, with a remarkable high expression of ZEB1 and PKCα in MDA-MB-231 and BT-549 basal-like cells, which display a significant degree of aggressiveness." (PMID 31828042, 2019). "The observed correlation between PKCα and ZEB1 in breast cancer cell lines prompted us to explore a direct link between them in more detail." (PMID 31828042, 2019). "Beyond the set of genes identified by this study, ZEB1 has also been shown to directly regulate the expression of IL-6 and other cytokines by breast cancer cells to promote accumulation of myeloid-derived suppressor cells in a mouse model of breast cancer." (PMID 31780722, 2019). "At the cellular level, miR-103/107 promotes EMT in breast cancer, attained by downregulating miR-200 levels, which targets the E-cadherin negative regulators ZEB1/2." (PMID 31766744, 2019). "We focused on MDA-MB-231 breast cancer cells, a model that shows high levels of expression of ZEB1 and PKCα, and in which ZEB1 function has been extensively studied." (PMID 31828042, 2019). "MDA-MB-231 is a mesenchymal breast cancer cell with high expression of ZEB1, providing an excellent model for studying ZEB1 transcriptional activity in a breast cancer model." (PMID 31780722, 2019). "We found that ZEB1 was uniformly and predominantly expressed in the stromal compartment of primary, xenografted and metastasised mammary tumours, a finding consistent with ZEB1 expression in human breast cancer." (PMID 31324807, 2019). "While interrogating the Cancer Genome Atlas (TCGA) and the Molecular Taxonomy of Breast Cancer International Consortium (METABRIC) data sets, we uncovered a significant association between ZEB1 levels and the tumour stromal abundances." (PMID 31324807, 2019). "The inverse relationship between ZEB1 and immune cell content was strongest in breast cancer (partial r = −0.5, r2 = 0.208)." (PMID 31780722, 2019). "Collectively, many studies have reported that honokiol effectively inhibits EMT in breast cancer cells, evidence has been found to support a cross-talk between honokiol and Stat3/Zeb1/E-cadherin axis." (PMID 31877856, 2019). "To further demonstrate that miR-190 mediates the regulation of SOX9 expression via ERα and ZEB1 in breast cancer cells, we transfected ERα plasmid into MDA-MB-231 cells in addition to E2 stimulation." (PMID 30658681, 2019). "We previously reported that the expression of ZEB1/2 is positively correlated with EMT phenotypes of breast cancer cell lines." (PMID 31682640, 2019). "miR‐200c inhibits the Wnt pathway by ZEB1, which can lead tometastasis and resistance in breast cancer." (PMID 31599500, 2019). "The findings reported herein support the notion that ZEB1 is an essential player of the metastatic phenotype in breast cancer cells." (PMID 31828042, 2019). "To expand on this finding, we bioinformatically explored the Heiser 2012 dataset (E-MTAB-181), where we cross-examined the mRNA levels of ZEB1 and PKCα in a larger panel of breast cancer cell lines." (PMID 31828042, 2019). "Our analyses revealed CAF-induced Ehi and E/M states, as exemplified by CAM6/CAM5/E-cad and E-cad/ZEB1 expressions in DCIS cells, respectively, to be associated with both the Her2+ER−PR− status and poor outcomes of breast cancer patients." (PMID 31331982, 2019). "Taken together, these findings demonstrate that an axis comprising PKCα-ZEB1 modulates the metastatic potential of breast cancer cells by promoting multiple mesenchymal features during the progression of the disease." (PMID 31828042, 2019). "The depletion of ZEB1 or overexpression of miR-200 family members in breast cancer cells with WISP2 depletion decreased PD-L1 expression levels." (PMID 30651114, 2019). "Taken together, these data demonstrate that RAE1 contributes to breast cancer metastasis by regulating a key EMT-inducing factor ZEB1 expression, suggesting its potential as a therapeutic target." (PMID 30814639, 2019).